RASSF6 (Ras association domain family member 6)
Description:
Involved in the induction of apoptosis, through both caspase-dependent and caspase-independent pathways. May act as a Ras effector protein. May suppress the serum-induced basal levels of NF-kappa-B (By similarity).
Tractability: PROTAC: ubiquitination databases record sites on it.
Gene: Protein-coding gene on chromosome 4 (73,571,550 to 73,620,631, reverse strand). Ensembl gene ENSG00000169435.
Subcellular location (Human Protein Atlas): Golgi apparatus; Nucleoplasm
Gene Ontology:
Molecular function: protein binding
Biological process: signal transduction; regulation of apoptotic process
Genetic constraint (gnomAD): Loss-of-function variants: 10 observed, 11.06 expected, observed/expected ratio (o/e) 0.9, 90% interval 0.56 to 1.52. The upper end of that interval is the gene's LOEUF score, 1.52, which puts it in group 6 of 6, group 1 being the genes least tolerant of losing a copy. Missense variants: 180 observed, 161.92 expected, observed/expected ratio (o/e) 1.11, 90% interval 0.98 to 1.26. Synonymous variants: 68 observed, 54.51 expected, observed/expected ratio (o/e) 1.25, 90% interval 1.02 to 1.53.
Homologues: Orthologues: chimpanzee RASSF6 (100% identical), macaque RASSF6 (97% identical), pig RASSF6 (85% identical), rabbit RASSF6 (83% identical), guinea pig RASSF6 (80% identical), mouse Rassf6 (77% identical), rat Rassf6 (76% identical), dog RASSF6 (71% identical), tropical clawed frog rassf6 (58% identical), zebrafish rassf6 (48% identical), Drosophila melanogaster Rassf (34% identical), Caenorhabditis elegans rsf-1 (14% identical). Paralogues in human: RASSF2 (38% identical), RASSF4 (36% identical), RASSF5 (19% identical), RASSF1 (16% identical), RASSF3 (14% identical).
Diseases named in the same sentence as RASSF6 in open-access papers:
RASSF6 is named in the same sentence as 35 diseases in open-access papers, as found by Europe PMC text mining. Sharing a sentence is not in itself a finding about the gene and the disease. The quoted sentences say what the papers report.
gastric cancer (9 papers, 2012 to 2022). A primary or metastatic malignant neoplasm involving the stomach. "Recently, RASSF6 was shown to be down-regulated at both mRNA and protein level in gastric cancer tumors and loss of RASSF6 expression correlated with poor survival and increased tumor recurrence rate." (PMID 22695170, 2012). "Downregulation of RASSF6 is involved in neuroblastoma, melanoma, nasopharyngeal cancer and childhood acute lymphocytic leukemia, and its decreased expression level is also associated with poor survival of pancreatic ductal adenocarcinoma and gastric cancer." (PMID 27009808, 2016). "Our findings highlight the interaction among the lncRNA, MALAT1, RASSF6 and β-catenin during tumorigenesis and progression of gastric cancer." (PMID 28077118, 2017). "It has previously been reported that expression of RASSF6 is correlated with invasion, lymph node metastasis, and advanced clinical stage in human gastric cancer." (PMID 28077118, 2017). "Accumulating evidence that low RASSF6 expression predicates poor prognosis in multiple gastrointestinal tumors, such as gastric cancer, hepatocellular carcinoma, pancreatic ductal adenocarcinoma." (PMID 28903410, 2017). "RASSF6 has been studied in multiple several tumors, including gastric cancer, melanoma, nasopharyngeal carcinoma, and pancreatic ductal adenocarcinoma." (PMID 28903410, 2017). "In particular, the metastasis-associated target gene, RASSF6, a member of the RAS-association domain family, is downregulated in gastric cancer, and its expression was upregulated by MALAT1 silencing, as revealed by genome-wide gene expression analysis." (PMID 28077118, 2017). "The suppression of RASSF6 is demonstrated at the mRNA level in clear cell renal carcinoma, pancreatic cancer, gastric cancer and metastatic nasopharyngeal cancer cell lines." (PMID 26690221, 2015). "It is demonstrated in gastric cancer cells whereby hsa-miR-181a-5p has been extensively studied and reported as a potential regulator of MEG2, a tumour suppressor gene, regulated RASSF6, and in combination predicts poor prognosis in gastric cancer." (PMID 35346116, 2022). "Moreover, enhanced expression of miR-181a promotes cell proliferation and inhibits apoptosis in gastric cancer by targeting MTMR340, via RASSF6-MAPK signaling activation." (PMID 32932883, 2020).
leukemia (5 papers, 2009 to 2024). A malignant (clonal) hematologic disorder, involving hematopoietic stem cells and characterized by the presence of primitive or atypical myeloid or lymphoid cells in the bone marrow and the blood. "Nevertheless, inactivation of RASSF6 or RASSF10 by promoter DNA hypermethylation appears to be an event associated with the majority of childhood leukaemias." (PMID 19570220, 2009). "For instance, Hesson and collaborators have reported that RASSF6 and RASSF10, tumor suppressor genes of the Ras-association family (RASSF), are hypermethylated in leukemia cells." (PMID 39308891, 2024). "In summary, we show that the hypermethylation profile of RASSF genes in leukaemias is distinct from that of solid tumours and show for the first time that RASSF6 is also inactivated in cancer, but specifically in leukaemias." (PMID 19570220, 2009). "This study shows the hypermethylation profile of RASSF genes in leukaemias is distinct from that of solid tumours and represents the first report of inactivation of RASSF6 or RASSF10 in cancer." (PMID 19570220, 2009). "Bisulphite sequencing of up to 12 individual alleles from 9 leukaemia cell lines, 6 B-ALL, 6 T-ALL, 1 pre-B-ALL, 6 normal blood and 1 normal bone marrow sample confirmed leukaemia-specific methylation across the entire RASSF6 CpG island in cell lines, B-ALL and T-ALL." (PMID 19570220, 2009). "Epigenetic inactivation of RASSF6 and RASSF10 is an extremely frequent event in the pathogenesis of childhood leukemia." (PMID 26334503, 2015). "RASSF6, located at chromosome region 4q13.3 has recently been suggested as a TSG candidate in childhood leukemia and was found to be silenced by heavy methylation across the whole CpG island in leukemia cell lines." (PMID 22695170, 2012). "Treatment of hypermethylated leukaemia cell lines with 5azaDC and TSA (Trichostatin A) reactivated RASSF6 expression." (PMID 19570220, 2009). "Using a commercially available antibody that recognises human RASSF6 protein we also observed restoration of RASSF6 protein expression following 5azaDC and TSA treatment in protein lysates from leukaemia lines." (PMID 19570220, 2009). "COBRA and bisulphite sequencing revealed RASSF6 and RASSF10 were the only RASSF members with a high frequency of leukaemia-specific methylation." (PMID 19570220, 2009). "A summary of RASSF6 and RASSF10 promoter methylation in leukaemia and control samples." (PMID 19570220, 2009). "Interestingly, such epigenetic silencing of RASSF6 and RASSF10 appeared to be extremely frequent in childhood leukemia, and were reversed by treatment with the hypomethylating drug decitabine, underlying the potential of epigenetic drugs in the treatment of HMs." (PMID 39308891, 2024). "Whilst RT-PCR showed RASSF6 was expressed in all normal tissues analysed including bone marrow, and in the unmethylated leukaemia cell line U937, we observed absent or downregulated expression of RASSF6 in methylated leukaemia cell lines." (PMID 19570220, 2009). "Surprisingly, we found that RASSF1–5 were infrequently methylated whilst RASSF6 was methylated in B-ALL (94%; 48/51), T-ALL (41%; 12/29) and 5/5 unclassified childhood leukaemias but not in normal blood or bone marrow control samples (0/8 and 0/1 respectively)." (PMID 19570220, 2009).
melanoma (5 papers, 2015 to 2021). A malignant, usually aggressive tumor composed of atypical, neoplastic melanocytes. "RASSF6 inhibits invasion in melanoma cells and enhances the sensitivity of highly metastatic nasopharyngeal carcinoma cells to cisplatin." (PMID 28903410, 2017). "However, epigenetic suppression of RASSF6 is also reported for childhood leukemia, melanoma, and neuroblastoma cell lines." (PMID 26690221, 2015). "Interestingly, the RASSF6 tumor suppressor gene exhibited its highest methylation frequency in melanoma brain metastases." (PMID 26198249, 2015). "The observation of the bona fide TSGs affected by promoter hypermethylation in CMM suggests that these molecules, e.g., TCF21, SOCS, RUNX, RASSF6, RASSFA, RARβ, MAPK13, H- and E-cadherin and AGTR, are a candidate for the design of new therapeutic strategies for human melanoma." (PMID 34639015, 2021). "For example, in melanoma, RASSF6 suppresses MAPK activation; whether RASSF6 also inhibits MAPK signalling in CRC, and whether Wnt is the primary mechanism that mediates the regulation of RASSF6 in CRC remains to be determined." (PMID 28903410, 2017).
colorectal cancer (4 papers, 2012 to 2020). A primary or metastatic malignant neoplasm that affects the colon or rectum. "In this study, we investigated the biological and clinical significance of RASSF6 in colorectal cancer as well as the underlying molecular mechanisms." (PMID 28903410, 2017). "We found that low RASSF6 expression corresponds to a poor prognosis in colorectal cancer patients, and low RASSF6 expression is distinctly associated with tumour progression." (PMID 28903410, 2017). "However, whether RASSF6 has an antitumor effect on colorectal cancer cells and the underlying regulation mechanisms remain unknown." (PMID 27009808, 2016). "However, whether RASSF6 is associated with colorectal cancer and the underlying mechanisms have yet to be investigated." (PMID 27009808, 2016). "Collectively, these findings provide new perspectives for the future study of RASSF6 as a therapeutic target for colorectal cancer." (PMID 28903410, 2017). "In this study, we demonstrated that RASSF6 is a tumour suppressor in colorectal cancer and may serve as a promising novel therapeutic target for colorectal cancer." (PMID 28903410, 2017). "Therefore, we conclude that RASSF6 inhibits tumour proliferation and metastasis in colorectal cancer." (PMID 28903410, 2017). "Our data suggest that RASSF6 may emerge as a new prognostic marker and an effective therapeutic target in colorectal cancer." (PMID 28903410, 2017). "Furthermore, the hypomethylation of RASSF6 protein in lung cancer samples was observed, which was in contrast to current literature, which suggests the hypermethylation of RASSF6 genes leads to the poor prognosis in colorectal cancer." (PMID 33143142, 2020).
neuroblastoma (4 papers, 2012 to 2016). Neuroblastoma (NB) is the most common solid, extracranial childhood tumor. "RASSF5 and RASSF6 were to various degrees methylated in a large portion of neuroblastoma tumors and RASSF7 was heavily methylated in most tumors." (PMID 22695170, 2012). "In the current study, we found that several of the RASSF family genes (RASSF2, RASSF4, RASSF5, RASSF6, RASSF7, and RASSF10) to various degrees were methylated in neuroblastoma cell lines and primary tumors." (PMID 22695170, 2012). "The genes RASSF5, RASSF6 and RASSF7 stand out as the most promising candidate genes for further investigations in neuroblastoma." (PMID 22695170, 2012). "However, in neuroblastoma, RASSF6 and RASSF7 showed a promoter methylation and RASSF6 promoter methylation was correlated with an unfavorable outcome." (PMID 25750636, 2015).
acute lymphoblastic leukemia (3 papers, 2021 to 2025). Leukemia with an acute onset, characterized by the presence of lymphoblasts in the bone marrow and the peripheral blood. "For example, the presence of DNA hypermethylation of RASSF6 and RASSF10 always indicates a poor prognosis in acute lymphoblastic leukemia (ALL)." (PMID 35865472, 2022). "Methylation status of RASSF6 and RASSF10 were assessed in a sample of Iranian Acute lymphocytic leukemia (ALL) cases." (PMID 33883026, 2021). "In acute lymphoblastic leukemia (ALL), there is a high prevalence of aberrant RASSF6 promoter methylation, and its DNA methylation status has the potential to serve as a biomarker for assessing MRD levels in ALL patients." (PMID 41140666, 2025). "It was observed that the RASSF6 methylation was more frequent in B-Cell Acute Lymphoblastic Leukemia (B-ALL) cases compared with T-cell acute lymphoblastic leukaemia (T-ALL) cases, whereas the RASSF10 hyper methylation was more frequent in T-ALL compared with pre-B-ALL and B-ALL patients." (PMID 33883026, 2021).
breast carcinoma (2 papers, 2018 to 2025). "RASSF6 is recognized as a tumor suppressor that is downregulated in various cancers, including breast cancer." (PMID 41153630, 2025). "In our study, RASSF6 was consistently downregulated across all breast cancer subtypes, indicating a subtype-independent mechanism for Hippo pathway impairment." (PMID 41153630, 2025). "In luminal A breast cancer, reduced expression of RASSF6 and STK4 correlated with poorer OS." (PMID 41153630, 2025). "In non-luminal HER2-positive breast cancer, reduced RASSF6 expression was linked with poorer OS." (PMID 41153630, 2025). "The subsequent step involved evaluating whether BIRC5, FGF1, RASSF6, SERPINE1 and STK4 could serve as targets for miRNAs differentiating breast cancer from the control." (PMID 41153630, 2025). "BIRC5, FGF1 and RASSF6 are unlikely to be targets of miRNAs significantly altered across five breast cancer subtypes in this study." (PMID 41153630, 2025).
bladder cancer (1 paper, 2012). "We studied DNA promoter methylation of five RASSF family members (RASSF1A, RASSF2A, RASSF4, RASSF5, and RASSF6) in FFPE bladder cancer tissues and normal adjacent tissues." (PMID 22530128, 2012).
colon cancer (1 paper, 2016). "It will be especially interesting to dissect the mechanism RASSF6 plays in the colon cancer model and its interaction with other molecules in signaling pathways." (PMID 27009808, 2016). "In this study, we demonstrate that RASSF6 acts as a tumor suppressor in colon cancer cells." (PMID 27009808, 2016).
colorectal adenocarcinoma (1 paper, 2016). The most common type of colorectal carcinoma. "To verify the expression level of RASSF6 in CRC, we carried out immunohistochemistry in a panel of tissue array containing 52 samples of colorectal adenocarcinoma and adjacent normal colon tissue." (PMID 27009808, 2016). "No significance was observed between RASSF6 expression and age, sex of 52 colorectal adenocarcinoma." (PMID 27009808, 2016).
ependymoma (1 paper, 2024). A WHO grade II, slow growing tumor of children and young adults, usually located intraventricularly. "BST1, FLG, KANK4, and SHISA9 were significantly higher expressed in SP-EPN subtype A compared to all other ependymomas, whereas AK5, CFTR, RASSF6, and TBX22 showed high expression in subtype B." (PMID 38265489, 2024).
glaucoma (1 paper, 2022). Increased pressure in the eyeball due to obstruction of the outflow of aqueous humor. "However, the association of C7, RASSF6 and GC-induced glaucoma is not known and warrants further investigation." (PMID 35585182, 2022).
infections in the skin (1 paper, 2016). "More interesting, we found five genes (CDKN2A, COL8A2, RASSF6, TMC4, and TMC5) from our 145 genes are associated with Walt’s disease (corrected P-value = 0.0040), which are infections in the skin caused by the human papillomavirus (HPV)." (PMID 27830726, 2016).
Nephropathy (1 paper, 2022). A nonspecific term referring to disease or damage of the kidneys. "The same animal study suggests the involvement of the RASSF6 pathway in contrast-induced nephropathy." (PMID 35697829, 2022).
Obesity (1 paper, 2013). Accumulation of substantial excess body fat. "Taken together, this suggests that the dramatic decrease in RASSF6 expression in obese adipose tissue could be involved in the control of the differentiation state and/or number of adipocytes during the course of obesity." (PMID 23626755, 2013).
renal carcinoma (1 paper, 2015). A carcinoma arising from the epithelium of the renal parenchyma or the renal pelvis. "In renal carcinoma cells, RASSF6 activates c-Jun N-terminal kinase (JNK) and JNK inhibitor suppresses RASSF6-induced apoptosis." (PMID 26690221, 2015).
trachoma (1 paper, 2009). "Here we show that the risk effect on trachoma maps to the region bounded by the AFM+1666 and IL-251 markers which contains RASSF6." (PMID 20015396, 2009).